TNFRSF18 (TNF receptor superfamily member 18)
Description:
Receptor for TNFSF18. Seems to be involved in interactions between activated T-lymphocytes and endothelial cells and in the regulation of T-cell receptor-mediated cell death. Mediated NF-kappa-B activation via the TRAF2/NIK pathway.
Synonyms: CD357; AITR; GITR; ENERGEN; GITR-D
Tractability: Antibody: a drug acting on it is in phase 2 or 3 trials; its Gene Ontology location is reachable by antibodies, with high confidence; UniProt places it where antibodies can reach, with medium confidence; UniProt predicts a signal peptide or a membrane-spanning region.
Target class: Membrane receptor
Gene: Protein-coding gene on chromosome 1 (1,203,508 to 1,206,592, reverse strand). Ensembl gene ENSG00000186891.
Subcellular location: Cell membrane (Isoform 1); Secreted (Isoform 2)
Pathways (Reactome):
Gene expression (Transcription): RUNX1 and FOXP3 control the development of regulatory T lymphocytes (Tregs)
Immune System: TNFs bind their physiological receptors
Gene Ontology:
Molecular function: protein binding; tumor necrosis factor receptor activity
Biological process: positive regulation of cell adhesion; positive regulation of leukocyte migration; positive regulation of tyrosine phosphorylation of STAT protein; negative regulation of apoptotic process; signal transduction; tumor necrosis factor-mediated signaling pathway
Cellular component: external side of plasma membrane; plasma membrane; extracellular region
Genetic constraint (gnomAD): Loss-of-function variants: 34 observed, 28.17 expected, observed/expected ratio (o/e) 1.21, 90% interval 0.92 to 1.61. The upper end of that interval is the gene's LOEUF score, 1.61, which puts it in group 6 of 6, group 1 being the genes least tolerant of losing a copy. Missense variants: 369 observed, 325.36 expected, observed/expected ratio (o/e) 1.13, 90% interval 1.04 to 1.24. Synonymous variants: 173 observed, 144.46 expected, observed/expected ratio (o/e) 1.2, 90% interval 1.06 to 1.36.
Homologues: Orthologues: chimpanzee TNFRSF18 (83% identical), macaque TNFRSF18 (73% identical), dog TNFRSF18 (63% identical), guinea pig TNFRSF18 (59% identical), rat Tnfrsf18 (59% identical), pig TNFRSF18 (55% identical), mouse Tnfrsf18 (49% identical), zebrafish cd40 (15% identical), zebrafish tnfrsf11a (15% identical), zebrafish tnfrsf1b (15% identical), tropical clawed frog nradd (13% identical), zebrafish nradd (13% identical), and 2 more. Paralogues in human: TNFRSF4 (21% identical), TNFRSF1B (21% identical), TNFRSF11A (17% identical), TNFRSF21 (16% identical), LTBR (15% identical), NGFR (15% identical), TNFRSF8 (15% identical), TNFRSF9 (15% identical), CD40 (13% identical), TNFRSF14 (13% identical), TNFRSF6B (13% identical), TNFRSF11B (12% identical), and 9 more.
Diseases named in the same sentence as TNFRSF18 in open-access papers:
TNFRSF18 is named in the same sentence as 157 diseases in open-access papers, as found by Europe PMC text mining. Sharing a sentence is not in itself a finding about the gene and the disease. The quoted sentences say what the papers report.
melanoma (50 papers, 2009 to 2025). A malignant, usually aggressive tumor composed of atypical, neoplastic melanocytes. "Recently, the first in-human phase-I trial of anti-TNFRSF18 (TRX518) was initiated in stage III or IV malignant melanoma (NCT01239134)." (PMID 37488117, 2023). "Animal studies on TNFRSF18 have shown that this checkpoint is related with the development of bladder carcinoma, breast cancer, SCLC, and melanoma; the knockout of TNFRSF18 leads to the accumulation of tumor cells, and the high expression of BRCA/HNSC is a favorable prognostic indicator." (PMID 34367975, 2021). "Also, according to a recent study, TNFRSF18/GITR enhances T cell-mediated killing of melanoma cells." (PMID 34589486, 2021). "Previous findings from studies involving the agonistic TNFRSF18 antibody, TRX518, laid the groundwork for clinical trials in malignant melanoma or other solid cancers." (PMID 36039012, 2023).
breast carcinoma (19 papers, 2013 to 2025). "Not only in colorectal cancer (COAD), but TNFRSF18 and CXCL13 also have higher expression in tumour tissues across multiple tumour types, including breast cancer (BRCA) and stomach cancer (STAD), indicating that they may serve as a target for a broad range of cancers." (PMID 40770837, 2025).
glioblastoma (15 papers, 2016 to 2025). The most malignant astrocytic tumor (WHO grade IV). "Our model genes are also associated with immune therapy response in glioblastoma, including T cell co-stimulatory molecules like TNFRSF18 and TNFSF4." (PMID 38365809, 2024). "Similar associations were observed in the CGGA-glioblastoma cohort for CD40, CD276, TNFRSF14, and TNFSF14, except for TNFSF4 and TNFRSF18." (PMID 38365809, 2024). "Based on these findings, we established a risk signature comprised of CD276, TNFRSF14, TNFSF14, TNFSF4, CD40, and TNFRSF18 to predict OS and response to immune checkpoint blockade in glioblastoma patients." (PMID 38365809, 2024). "In addition, we obtained representative IHC staining images of CD276, TNFSF4, TNFRSF14, CD40, TNFSF14, and TNFRSF18 in both normal tissues and glioblastoma samples from the Human Proteome Atlas." (PMID 38365809, 2024). "In glioblastoma, a combination of anti-TNFRSF18 and anti-PD-1 antibodies exhibited satisfactory survival benefits by targeting Tregs, indicating this may be a promising strategy for anti-tumor immunotherapy." (PMID 38725845, 2024).
autoimmune disease (14 papers, 2009 to 2025). A disorder resulting from loss of function or tissue destruction of an organ or multiple organs, arising from humoral or cellular immune responses of the individual to their own tissue constituents. "CD4T1 and CD4T10 included genes for costimulatory molecules OX40 (TNFRSF4) and GITR (TNFRSF18), both of which have been described to promote survival and proliferation of CD4+ Teff and have been targets of autoimmune disease therapeutics." (PMID 38743491, 2024).
glioma (9 papers, 2013 to 2025). A benign or malignant brain and spinal cord tumor that arises from glial cells (astrocytes, oligodendrocytes, ependymal cells). "Beyond these two genes, TNF Receptor Superfamily Member 18 (TNFRSF18) and Matrix Metallopeptidase 19 (MMP19), also selected by both methods, have been associated with a poor prognosis in glioma." (PMID 40428295, 2025). "Notably, genes such as LOXL1, IGFBP6, TNFRSF18 and MMP19, identified by both methods, have established links to glioma survival." (PMID 40428295, 2025). "Thus, the TNFRSF18 and CD274 may have a great potential in the tumor immunotherapy of glioma." (PMID 40351420, 2025).
colorectal cancer (8 papers, 2012 to 2025). A primary or metastatic malignant neoplasm that affects the colon or rectum. "We next investigated the association of TNFRSF18 expression with T cell functional states and clonal expansion dynamics in colorectal cancer." (PMID 40770837, 2025). "This validation confirms the reliability of TNFRSF18 as one marker gene for exhausted T cells in colorectal cancer." (PMID 40770837, 2025). "Schematic model for TNFRSF18 decline fuels stemness‐driven immune evasion in colorectal cancer." (PMID 40770837, 2025). "Thus, the expression pattern of TNFRSF18 in different TNMs suggests its use as a target for early screening of colorectal cancer." (PMID 40770837, 2025). "We additionally examined the expression of TNFRSF18 and CXCL13 in colorectal cancer and other tumours through the GEPIA database." (PMID 40770837, 2025). "This study revealed that with advancing TNM staging of colorectal cancer (CRC), TNFRSF18 expression in CD8+ T cells progressively decreased, while CXCL13 expression increased." (PMID 40770837, 2025). "In addition, CD8+ T cells exhibited elevated TNFRSF18 expression in colorectal cancer samples with liver metastasis, whereas CXCL13 was higher in CD8+ T cells from non‐metastatic colorectal cancer samples." (PMID 40770837, 2025).
lung carcinoma (7 papers, 2016 to 2024). "In another study, scRNA-seq and ST were applied to characterize the cellular composition and spatial structure of multiple primary lung cancers (MPLCs), finding that TNFRSF18 was highly expressed in T&NK cells within tumor tissues." (PMID 39334490, 2024). "TNFRSF18 has been demonstrated to be associated with non-response to anti-PD-1 therapy in lung cancer." (PMID 39334490, 2024). "Besides, TEDC2 expression was also correlated with TNFRSF25, TNFRSF4 and TNFRSF18 in our analysis, which might be correlated with immune evasion and poor outcome in lung cancer, but the molecular mechanisms of these immune checkpoint molecules still remain elusive and need further investigation." (PMID 36973475, 2023). "TNFRSF18 was found highly expressed in Tregs of lung cancer tumor tissues which were non-responsive to anti-PD-1 therapy." (PMID 37488117, 2023).
hepatocellular carcinoma (6 papers, 2022 to 2025). A malignant tumor that arises from hepatocytes. "However, single-cell RNA sequencing data from hepatocellular carcinoma (HCC) patients has identified TNFRSF18 as a key Tex gene associated with high-risk groups and poor patient survival." (PMID 40236693, 2025). "We found that ITM2A, LTB, TNFRSF4, and TNFRSF18 were significantly overexpressed in hepatocellular carcinoma cell lines (Hep3B and Huh7) relative to normal liver cell lines (HL-7702)." (PMID 37006257, 2023).
colon cancer (5 papers, 2013 to 2024). "The TNFRSF18 and TNFSF12 genes are related to tumor necrosis factor (TNF), which is a well-known inflammatory biomarker that promotes cytokines in colon cancer." (PMID 33670198, 2021).
allergic asthma (4 papers, 2009 to 2025). A asthma with a basis in a pathological type I hypersensitivity reaction. "Specifically, the activation of TNFRSF18 also called glucocorticoid-induced TNFR family-related protein (GITR), has been shown to promote the features of allergic asthma and the differentiation of Th2 cells in vitro." (PMID 40089475, 2025).
diabetes (4 papers, 2009 to 2025). "It has been shown that blocking TNFRSF18 expression can prevent the onset of diabetes." (PMID 40597598, 2025). "Collectively, these findings suggest that PET microplastics may increase the risk of β-cell damage and contribute to the development of diabetes by upregulating key cytokines such as IL-12β, TNFSF3, TNFSF14 and TNFRSF18." (PMID 40597598, 2025).
endometrial cancer (4 papers, 2019 to 2024). Primary or metastatic malignant neoplasm involving the endometrium (mucous membrane that lines the endometrial cavity). "TNFRSF18 plays a crucial role in modulating immune response and inflammation and is known as a reliable biomarker that can predict the prognosis of patients with endometrial cancer." (PMID 36253800, 2022). "In another study, a six-gene prognostic signature, including CTSW, PCSK4, LRRC8D, TNFRSF18, IHH, and CDKN2A, in endometrial cancer was also established using robust likelihood-based survival modeling." (PMID 31781484, 2019).
head and neck squamous cell carcinoma (4 papers, 2018 to 2025). A squamous cell carcinoma that arises from any of the following anatomic sites: lip and oral cavity, nasal cavity, paranasal sinuses, pharynx, larynx, and salivary glands. "TNFRSF18 was served as an immunostimulator that was overexpressed in head and neck squamous cell carcinoma." (PMID 35622386, 2022).
malaria (4 papers, 2010 to 2023). Malaria is a serious and sometimes fatal disease caused by a parasite that commonly infects a certain type of mosquito which feeds on humans. "To summarize, selected regulatory SNPs in the promoter region of FOXP3, IL10RA, IL10RB, STAT6 and TNFRSF18 genes have been investigated for possible association with uncomplicated malaria and high P. falciparum parasite density among Congolese children." (PMID 23297791, 2013).
Multiple Myeloma (4 papers, 2013 to 2021). "Recently tumor necrosis factor receptor super family member 18 (TNFRSF18, also called GITR) has been identified as a novel tumor suppressor gene in Multiple Myeloma (MM), undergoing aberrant DNA methylation-mediated gene expression silencing." (PMID 25973846, 2015).
Sepsis (3 papers, 2016 to 2025). Sepsis is defined as life-threatening organ dysfunction caused by a dysregulated host response to infection. "In addition, the expression of FOXP3, CTLA4, TIGIT, TNFRSF18, and IL2RA, key functional genes of Tregs, was increased in the E-SEP group, suggesting that the immunosuppressive effect of Tregs was enhanced in the elderly with sepsis." (PMID 38909272, 2024).
visceral leishmaniasis (3 papers, 2012 to 2024). A severe form of leishmaniasis characterized by irregular bouts of fever, substantial weight loss, swelling of the spleen and liver, and anemia (which may be serious). "TNFRSF18 stimulation improves the therapeutic drug response in visceral leishmaniasis and CD23 (FcεRII) participates of the nitric oxide control of L. braziliensis infection." (PMID 23029578, 2012).
cervical carcinoma (2 papers, 2008 to 2022). A carcinoma arising from either the exocervical squamous epithelium or the endocervical glandular epithelium. "These include the up-regulation of TNFRSF18 (also known as glucocorticoid-induced TNFR-related gene) and the survival factor erythropoietin which has been shown to be involved in survival of human breast and cervix carcinoma cells." (PMID 18691394, 2008).
small cell lung carcinoma (2 papers, 2020 to 2024). Small cell lung cancer (SCLC) is a highly aggressive malignant neoplasm, accounting for 10-15% of lung cancer cases, characterized byrapid growth, and early metastasis. "In small cell lung cancer, TNFRSF18 has been found to bind to its receptor and induce apoptosis." (PMID 32699529, 2020).
thyroid cancer (2 papers, 2020 to 2024). "Finally, we introduced a case study, enhancer: chr1:1186391–1186507 ∼ miR-200a was highly relevant to the survival of thyroid cancer patients and a cis-eQTL SNP on the enhancer affected the expression of the TNFRSF18 gene as a tumor suppressor." (PMID 32714372, 2020). "Finally, we introduced a case study, enhancer: chr1:1186391–1186507 ∼ miR-200a was highly relevant to the survival of thyroid cancer patients and a cis-eQTL SNP on enhancer affected the expression of the TNFRSF18 gene, a tumor suppressor." (PMID 32714372, 2020). "Finally, a case study was introduced, enhancer: chr1:1186391–1186507 ∼ miR-200a was highly relevant to the survival of thyroid cancer patients and the cis- expression quantitative trait loci (eQTL) SNP on the enhancer affected the expression of the TNFRSF18 gene as a tumor suppressor." (PMID 32714372, 2020).
autoinflammatory syndrome (1 paper, 2013). A group of disorders of the innate immune system characterized by attacks of seemingly unprovoked inflammation without significant levels of either autoantibodies or autoreactive T cells more characteristic of autoimmune disease. "Also, the expression of key surface molecules by TR2-deficient Treg cells—namely CTLA-4, GITR (Tnfrsf18), and ICOS —remained unchanged in contrast to our observations in the bone marrow chimera model presenting with a lethal autoinflammatory syndrome." (PMID 24115907, 2013).
cryptorchidism (1 paper, 2020). The failure of one or both testes of a male fetus to descend from the abdomen into the scrotum during the late part of pregnancy. "The present study revealed the PMF, PCA and a novel candidate associated with porcine cryptorchidism, TNFRSF18, at 15 weeks of age." (PMID 33008399, 2020). "The present study revealed the specific PMFs and clusters for porcine cryptorchidism, and a novel protein, TNFRSF18, associated with the disease mechanism." (PMID 33008399, 2020).
mucinous ovarian cancer (1 paper, 2013). An invasive malignant neoplasm that arises from the ovary and is characterized by the presence of malignant epithelial cells that contain intracytoplasmic mucin and may resemble the epithelial cells of the endocervix or gastrointestinal tract. "We report an association between risk of death due to mucinous ovarian cancer and a SNP in a gene cluster containing TNFRSF18 and TNFRSF4." (PMID 23382860, 2013). "One other SNP rs3753348 showed association with a more than three-fold risk with survival in mucinous ovarian cancer; this SNP resides in the 5 kb region between tumor necrosis factor receptor superfamily members 4 and 18 (TNFRSF4 and TNFRSF18) on chromosome 1." (PMID 23382860, 2013).
sarcoma (1 paper, 2022). A usually aggressive malignant neoplasm of the soft tissue or bone. "Analysis of the transcript levels of the costimulatory receptors OX40/TNFRSF4, ICOS, and GITR/TNFRSF18 indicated that ICOS and GITR transcripts were not highly expressed in any sarcoma subtype relative to other cancers in the TCGA dataset." (PMID 35558159, 2022).